MORN5 (MORN repeat containing 5)
Synonyms: C9orf113; C9orf18; FLJ46909
Tractability: No criterion of Open Targets' tractability assessment is met for any kind of drug.
Gene: Protein-coding gene on chromosome 9 (122,159,903 to 122,200,088, forward strand). Ensembl gene ENSG00000185681.
Subcellular location: Cell projection, cilium, flagellum
Gene Ontology:
Molecular function: protein binding
Cellular component: sperm flagellum; motile cilium
Genetic constraint (gnomAD): Loss-of-function variants: 18 observed, 21.44 expected, observed/expected ratio (o/e) 0.84, 90% interval 0.58 to 1.25. The upper end of that interval is the gene's LOEUF score, 1.25, which puts it in group 5 of 6, group 1 being the genes least tolerant of losing a copy. Missense variants: 201 observed, 217.12 expected, observed/expected ratio (o/e) 0.93, 90% interval 0.82 to 1.04. Synonymous variants: 71 observed, 74.99 expected, observed/expected ratio (o/e) 0.95, 90% interval 0.78 to 1.15.
Homologues: Orthologues: chimpanzee MORN5 (99% identical), pig MORN5 (83% identical), rabbit MORN5 (83% identical), guinea pig MORN5 (82% identical), macaque MORN5 (81% identical), mouse Morn5 (79% identical), rat Morn5 (76% identical), dog MORN5 (72% identical), tropical clawed frog morn5 (72% identical), zebrafish morn5 (65% identical).
Diseases named in the same sentence as MORN5 in open-access papers:
MORN5 is named in the same sentence as 2 diseases in open-access papers, as found by Europe PMC text mining. Sharing a sentence is not in itself a finding about the gene and the disease. The quoted sentences say what the papers report.
cleft lip (1 paper, 2016). Congenital defect in the upper lip where the maxillary prominence fails to merge with the merged medial nasal prominences. "Previously, a human genetics study found that MORN5 was associated with non-syndromic cleft lip with or without cleft palate (NSCLP)." (PMID 27630576, 2016). "The restricted expression of MORN5 in the lip fusion zone shown here supports the human genetic data in which MORN5 variants were associated with increased risk of non-syndromic cleft lip with or without cleft palate." (PMID 27630576, 2016).
MORN5 also shares sentences with these, for which no sentence is quoted: cleft palate (1 paper).